BRCA1 (BRCA1 DNA repair associated)
Diseases named in the same sentence as BRCA1 in open-access papers (continued):
Sharing a sentence is not in itself a finding about the gene and the disease.
skin cancer (16 papers, 2016 to 2025). "Overall, between age 40 and 79 the annual risk for any skin cancer was 0.5% for BRCA1 carriers and 0.6% for BRCA2 carriers." (PMID 38741145, 2024). "We estimated the cumulative risk of any skin cancer from age 20 to 80 to be 14.1% for BRCA1 mutation carriers and 10.7% for BRCA2 mutation carriers." (PMID 38741145, 2024). "The cumulative risk of all types of skin cancer from age 20 to 80 years was 14.1% for BRCA1 carriers and 10.7% for BRCA2 carriers." (PMID 38741145, 2024). "We estimated the annual and cumulative risk of skin cancer in women who carry BRCA1 or BRCA2 mutations." (PMID 38741145, 2024). "Women from the United States had a higher risk of skin cancer than those from Canada (HR = 1.98, 95% CI: 1.39, 2.83, p < 0.0001) for BRCA1 carriers and HR = 1.55 (95%CI 1.04–2.30; p = 0.03) for BRCA2 carriers." (PMID 38741145, 2024). "We found the cumulative risk of all types of skin cancer reported in this cohort from age 20 to 80 years to be 14.1% for BRCA1 mutation carriers and 10.7% for BRCA2 mutation carriers." (PMID 38741145, 2024). "A previous diagnosis of skin cancer was reported by 3.4% of BRCA1 mutation carriers and by 4.1% of BRCA2 mutation carriers." (PMID 38741145, 2024). "BRCA1/2 germline mutations predispose carriers to an increased risk of breast, ovarian, prostate, pancreatic, and skin cancer." (PMID 35448177, 2022). "Moreover, BRCA1/2 carriers are also at a greater risk of developing other cancers, including prostate, pancreatic, and skin cancer." (PMID 35448177, 2022). "However, as suggested by other authors, patient carriers of a BRCA1/BRCA2 mutations should be informed about the risk of skin cancer and be subjected to a periodic dermatological control." (PMID 29346284, 2018). "The evidence linking BRCA1/2, ATM, CHEK2, BRIP1, and FH pathogenic variants to increased skin cancer risk is limited." (PMID 41331641, 2025). "Future studies will be conducted to better estimate the lifetime cumulative rate of skin cancer among BRCA1 and BRCA2 carriers." (PMID 38741145, 2024). "Also, LHCGR is expressed by the BRCA1 conditional knockout mouse skin tumor tissue." (PMID 28869585, 2017). "To conclude, in this cohort of young women with a BRCA1/2 GPV, more cases of head and neck cancer, gastrointestinal cancer, skin cancer, and female genital tract cancer were observed before the age of 60 compared to the general population." (PMID 40427184, 2025). "There are no established guidelines for skin cancer screening in BRCA1/2 carriers; however, the NCCN guidelines propose skin exploration annually for patients with pathogenic variants in the BRCA2 gene." (PMID 40649916, 2025). "Finally, we compare the frequency of mutations of the core HR genes BRCA1/2, CHEK2 and PALB2 in non-melanoma skin cancers." (PMID 34084283, 2021).
cholangiocarcinoma (15 papers, 2018 to 2025). A carcinoma that arises from the intrahepatic biliary tree (intrahepatic cholangiocarcinoma) or from the junction, or adjacent to the junction, of the right and left hepatic ducts (hilar cholangiocarcinoma). "We present the first reported case of a patient diagnosed with cholangiocarcinoma found to have mutations in both BRCA1 and BRCA2 genes." (PMID 38903278, 2024). "We describe a case of a woman with cholangiocarcinoma with transheterozygous BRCA1 and BRCA2 co-mutations who failed initial chemotherapy and was treated with targeted therapy for BRCA-positive patients." (PMID 38903278, 2024). "Although BRCA-associated cholangiocarcinomas are uncommon, even rarer is a mutation in both BRCA1 and BRCA2 genes." (PMID 38903278, 2024). "There are multiple documented genomic mutations associated with cholangiocarcinoma, and this includes the BRCA1 and BRCA2 genes." (PMID 38903278, 2024). "We present a case of a patient with cholangiocarcinoma found to have mutations in both BRCA1 and BRCA2 genes." (PMID 38903278, 2024). "Cholangiocarcinoma patients with BRCA1/2 mutations treated with PARP inhibitors exhibited a favorable response." (PMID 32631434, 2020). "KKU-213, an HR-proficient cholangiocarcinoma cell line, was used to examine whether suppression of BRCA1 or BRCA2 expression sensitizes the cells to E7820." (PMID 38789724, 2024). "Further study of this case, as well as future transheterozygous BRCA1 and BRCA2 cholangiocarcinomas, may provide further information on patients of this population and define a more targeted approach for individualized treatments." (PMID 38903278, 2024).
head and neck cancer (15 papers, 2008 to 2025). A primary or metastatic malignant neoplasm affecting the head and neck. "Another aspect is that when patients are treated with more toxic regimens, such as in head and neck cancer, and there is a BRCA1/2 variant with increased radiosensitivity, the risk of adverse therapeutic effects would increase significantly." (PMID 37623237, 2023). "In this review, the identification of head and neck cancers, apart from those that have BRCA-1 and 2 mutations, which would be sensitive to PARP inhibitors by using different biomarkers, was pointed out as an important issue and discussed in some detail." (PMID 36612094, 2022). "We also show that phenylbutyrate can sensitize FA/BRCA1-deficient head and neck cancer cells suggesting additional target for cisplatin sensitization by phenylbutyrate." (PMID 18325101, 2008). "Altogether, these findings strongly suggest that miR-205-5p significantly impacts the DNA repair ability of head and neck cancer cells through the repression of BRCA1 and RAD17 gene expression." (PMID 31514456, 2019). "Among the BRCA1-mutated families, the most frequent tumours were CRC, lung, gastric, and head and neck cancer (16, 14, 12 and 12%, respectively)." (PMID 29884136, 2018). "If the cisplatin-sensitizing activity of phenylbutyrate is chiefly due to the inhibition of the FA/BRCA1 pathway, then phenylbutyrate should have only limited ability to sensitize head and neck cancer cell lines that are defective in the FA/BRCA1 pathway." (PMID 18325101, 2008). "In this study we show that phenylbutyrate treatment leads to a down-regulation of BRCA1 in all three head and neck cancer cell lines tested." (PMID 18325101, 2008). "To test whether phenylbutyrate may affect the expression of BRCA1 in head and neck cancer cells, we analyzed the BRCA1 protein levels in mock-treated and phenylbutyrate-treated cells using Western blot." (PMID 18325101, 2008). "However, when these experiments were performed using another head and neck cancer cell line (UM-SSC-14A) that also has a defect in the FA/BRCA1 pathway, a clear sensitization was observed." (PMID 18325101, 2008). "The results from this study suggest that phenylbutyrate may have therapeutic utility as a cisplatin sensitizer in head and neck cancer by inhibiting the FA/BRCA pathway through the down regulation of BRCA1 as well as by an FA/BRCA-independent mechanism." (PMID 18325101, 2008). "In addition, phenylbutyrate sensitized one head and neck cancer cell line with a defective FA/BRCA1 pathway to cisplatin suggesting that phenylbutyrate targets multiple pathways that normally protect cells against cisplatin." (PMID 18325101, 2008). "Others showed that BRCA1 or BRCA2 mutation does not increase head and neck cancer incidence." (PMID 34577828, 2021). "Furthermore, phenylbutyrate may, in addition to inhibiting the FA/BRCA1 pathway, act on additional targets to sensitize head and neck cancer cells to cisplatin." (PMID 18325101, 2008). "However, the role of ATM and BRCA1 gene expression in head and neck cancer (HNC) is not well characterized." (PMID 34068585, 2021).
head and neck squamous cell carcinoma (15 papers, 2011 to 2025). A squamous cell carcinoma that arises from any of the following anatomic sites: lip and oral cavity, nasal cavity, paranasal sinuses, pharynx, larynx, and salivary glands. "Somatic mutations in BRCA1 are seen in only 6% and BRCA 2 in 7% of head and neck squamous cell carcinoma (HNSCC) patients, indicating the multistep process involved in tumorigenesis." (PMID 40026996, 2025). "Mutations simultaneously affecting both BRCA1 and BRCA2 mainly occurred in head/neck squamous cell carcinoma (18.8%) and cutaneous melanoma (12.5%)." (PMID 33054725, 2020). "Experiments verified that the miR-205-5p/BRCA1/RAD17 axis increased the level of γ-H2AX and made DNA repair inefficient in head and neck squamous cell carcinomas in vivo and in vitro, revealed that miR-205-5p/BRCA1/RAD17 axis had the potential to be a therapeutic target for cancer." (PMID 35591858, 2022). "We initially evaluated whether miR-205-5p, a microRNA (miRNA) highly expressed in head and neck squamous cell carcinoma (HNSCC), targeted BRCA1 and RAD17 expression." (PMID 31514456, 2019). "The same study demonstrated a correlation of SMAD4 knockdown with the downregulation of BRCA1 and RAD51 protein expression in head and neck squamous cell carcinoma (HNSCC) as well as increased expression of TβR1 and phospho-SMAD3." (PMID 33418880, 2021). "Moreover, overexpression of SET fails to induce up-regulation of ATM, BRCA1 and CHK2 and recruitment of BRCA2 to DNA damage foci in head and neck squamous cell carcinoma (HNSCC) lines upon cisplatin treatment, suggesting another important inhibitory role of SET on DNA damage repair." (PMID 36345878, 2022).
hereditary non-polyposis colorectal cancer (14 papers, 1998 to 2023). "Ten per cent of all PDAC cases are related to genetic disorders, e.g. BRCA1 and BRCA2 gene mutations, hereditary non-polyposis colorectal cancer (HNPCC, Lynch syndrome) and familial atypical mole-malignant melanoma (FAMMM)." (PMID 22873581, 2012). "Recent literature reports state that the screening is only recommended for the high-risk population identified as those with a family history of the disease, women with BRCA1 and BRCA2 mutations, or with hereditary nonpolyposis colorectal cancer." (PMID 21577260, 2011).
nasopharyngeal carcinoma (14 papers, 2012 to 2024). A carcinoma arising from the nasopharyngeal epithelium. "A similar study in a nasopharyngeal carcinoma (NPC) (CNE2RR) cell line induced the expression of NFBD1, BRCA1, BRCA2, RPA1, and RAD51 proteins widely associated with HR and radioresistance." (PMID 34900673, 2021). "In this study, we examined ERCC1 and BRCA1 expression and clinical outcome of 201 phase-III-IV nasopharyngeal carcinoma patients who were treated with cisplatin-based induced chemotherapy and concurrent radiochemotherapy." (PMID 28404895, 2017). "UBC13, HLTF, and SHPRH in the TS pathway, RAD51 and BRCA1 in the HR pathway, and FANCD2 in the FA pathway are highly expressed in cisplatin-resistant nasopharyngeal carcinoma (NPC) cells." (PMID 25051366, 2014). "To determine the protein expression and clinical implications of DNA-PKcs and BRCA1 in nasopharyngeal carcinoma (NPC) and cancer progression, we evaluated its expression status by immunohistochemistry in 87 patients who received intensity-modulated radiation therapy (IMRT)." (PMID 23599763, 2013). "In conclusion, in nasopharyngeal carcinoma patients, ERCC1 and BRCA1 may be a predictor of response to platinum-based chemotherapy and concurrent radiochemotherapy." (PMID 28404895, 2017). "Moreover, western blotting unveiled that circCDYL2 promoted the expression levels of RAD51 protein in nasopharyngeal carcinoma cells, while it did not influence the expression of BRCA1, RPA1, or Ku70, a key protein within the NHEJ pathway." (PMID 38654320, 2024). "However, it has also been reported that an increase in the gene expression level of DDR genes may lead to resistance to cisplatin chemotherapy, while the overexpression of BRCA1, BRCA2, RAD51 and RPA1 has been observed in hypopharyngeal and nasopharyngeal carcinoma cells resistant to radiotherapy." (PMID 37740039, 2023). "Previous studies have revealed that CDK6 enhances radioresistance in human malignancies including nasopharyngeal cancer and HPV negative head and neck squamous cell carcinoma possibly by promoting RAD51 and BRCA1 expression and thereby activating homologous recombinational (HR) DNA repair after IR." (PMID 34395263, 2021).
retinoblastoma (14 papers, 2014 to 2025). A malignant tumor that originates in the nuclear layer of the retina. "Interestingly cells from cancer syndromes show either a maximal number of MRE11 foci from 10 min to 1 h after 2 Gy X-rays (e.g., retinoblastoma, tuberous sclerosis complex, and neurofibromatosis type 1) or the MRE11 foci are impaired (e.g., in BRCA1-, BRCA2-, BLM-, FANC-, and ATM-mutated cells)." (PMID 37626928, 2023). "In mammals BRCA1 interacts with MRN (MRE11-RAD50-NBS1), CtIP (COM1-SAE2), and Retinoblastoma, to activate G2 cell cycle check-point by means of ATM phosphorylation." (PMID 26147458, 2015).
atherosclerosis (13 papers, 2012 to 2025). A disease characterized by the build-up of fatty material and calcium deposition in the arterial wall resulting in partial or complete occlusion of the arterial lumen. "In regard to atherosclerosis, the loss of BRCA1 in cardiomyocytes was associated with a reduction in regulating cardiac energy supply, promoting endothelial cell apoptosis and endothelial dysfunction." (PMID 39621070, 2025). "BRCA1, a well-known tumor suppressor implicated in familial breast and ovarian cancers, provides a protective role in atherosclerosis and neurological diseases." (PMID 32381096, 2020). "Available evidence obtained from studies on animal models and human BRCA1 mutation carriers showed a correlation of BRCA1 deficiency with various cardiovascular diseases, such as ischemic heart disease, atherosclerosis, and cardiac muscle disorders linked to chemotherapy." (PMID 40561071, 2025). "DMRs in the promoter region of BRCA1 and CRISP2 were consistently associated with subclinical atherosclerosis measures, suggesting their potential blood surrogate markers for early risk stratification." (PMID 35534881, 2022). "For example, BRCA1 and CRISP2 specific site methylation changes are associated with atherosclerosis, indicating that differentially methylated regions of BRCA1 and CRISP2 emerge as biomarkers for CVD." (PMID 34262910, 2021). "As such, our results show that DNA hypermethylation of most BRCA1 and CRISP2 CpG probes occurs independently of sample variation in blood cell type composition and is associated with atherosclerosis pathology." (PMID 28698603, 2017). "Despite this, these studies collectively highlight the significance of BRCA1 in cardiovascular disease or atherosclerosis and moreover, our findings proposed BRCA1 may as a potential biomarker for diagnosing AAD." (PMID 40561071, 2025). "Further, given that OLA1 and BRCA1 regulate the cellular responses to oxidative stresses, it can be speculated that OLA1 and BRCA1 work together in the development of atherosclerosis." (PMID 36232807, 2022). "Furthermore, methylation in BRCA1 and CRISP2 DMR was also associated with subclinical atherosclerosis measures in an independent sample of middle age men." (PMID 28698603, 2017). "All results presented above showed that BRCA1 may play a protective role in cardiovascular disease and may be a represent potential therapeutic target to improve endothelial dysfunction and retard atherosclerosis." (PMID 40561071, 2025). "While BRCA1 is widely recognized as a tumor suppressor, recent evidence suggests that it may act as an anti-inflammatory protein to retard endothelial dysfunction and atherosclerosis." (PMID 40076974, 2025). "In order to get an insight about the cause and/or effect relationship of BRCA2 with atherosclerosis in ECs, we next measured BRCA2 expression levels in ECs treated with different doses (0, 5, 10, 20, 50, and 100 μg/ml) of oxLDL for 24 hr and measured BRCA1 and BRCA2 expression." (PMID 32638521, 2020). "Moreover, lipid and metabolite deregulation is observed in humans carrying either BRCA1 or BRCA2 (BRCA1/2) mutations and a genetic analysis identified BRCA2 SNPs’ association with plasma‐lipid levels, which plays an important role in endothelial dysfunction and atherosclerosis." (PMID 32638521, 2020). "Altogether, our data suggest that BRCA1 and CRISP2 DNA methylation patterns are potential epigenetic biomarkers related to atherosclerosis in blood and atherosclerotic plaque tissue matrix." (PMID 28698603, 2017).